TDRKH-AS1 (TDRKH antisense RNA 1)
Synonyms: RP11-98D18.9
Gene: Long non-coding RNA gene on chromosome 1 (151,790,709 to 151,794,403, forward strand). Ensembl gene ENSG00000203288.
Diseases named in the same sentence as TDRKH-AS1 in open-access papers:
TDRKH-AS1 is named in the same sentence as 1 disease in open-access papers, as found by Europe PMC text mining. Sharing a sentence is not in itself a finding about the gene and the disease.
TDRKH-AS1 shares sentences with these, for which no sentence is quoted: endothelial dysfunction (1 paper).